CRP (C-reactive protein)
Diseases named in the same sentence as CRP in open-access papers (continued):
Sharing a sentence is not in itself a finding about the gene and the disease.
Obesity (continued). "Weight loss has been shown to reduce pro-inflammatory markers present in the chronic low-grade inflammatory state associated with obesity, including CRP, IL-6 and TNF-a (Christiansenet al., 2010;Marfellaet al., 2004;Moelleret al., 2016) and may thereby help manage LC symptoms." (PMID 39145102, 2024). "Elevated CRP levels could lead to an increased risk of obesity." (PMID 38590820, 2024). "Minor changes in CRP level, as seen in our study, are likely to result from a low level of underlying chronic inflammation, which may accompany various conditions (e.g., specific dietary patterns, overweight, and obesity)." (PMID 39408337, 2024). "In BMI-stratified analyses, high CRP was associated with elevated risk of events in normal-weight and overweight (HRadj:1.70 [95% CI = 1.09–2.66]; HRadj:1.75 [95% CI = 1.08–2.86]), but in obesity, the estimate was less precise (HRadj:1.73 [95% CI = 0.78–3.83])." (PMID 38914635, 2024). "The dysregulation of adipocytokine secretion that occurs in obesity states was consistently associated with an increased secretion of a number of inflammatory factors, as these adipocytokines that are secreted from adipose tissue are involved in inducing the production of CRP." (PMID 37242271, 2023). "Furthermore, the diagnosis of MAFLD/MASLD-defined fatty liver disease based on a spectrum of metabolic syndromes including obesity may make CRP more applicable since both CRP and fatty liver are associated with metabolic disorders." (PMID 37893085, 2023). "The stronger correlation with CRP among the LCD sub-cohort—characterized by lower mean BMI—suggests that this association with systemic inflammation might be more pronounced in less severe obesity." (PMID 38255140, 2023). "Additionally, a correlation was confirmed between low EPA concentrations and vitamin A, hyperinsulinemia, and high CRP, which might increase the risk of insulin resistance and aggravate obesity-related inflammation." (PMID 37299442, 2023). "Concurring with the discussion above, CRP and omega-3 fatty acids are important parameters for consideration in obesity because they are associated with inflammation and metabolic health, which play significant roles in the development and management of obesity." (PMID 37754594, 2023). "Additionally, type 1 diabetes can be accompanied with increased CRP that can also be linked to underlying obesity, and a study concluded that elevated CRP may provide an extra marker for the risk of progression of this condition." (PMID 37873776, 2023). "The results demonstrated that obesity (BMI ≥24 kg/m2), high HR (>100/min), moderate disease severity, increased CK-MB and hs-cTnI were independent risk factors for arrhythmia in infected patients (p < 0.05), while elevated hs-CRP was a protective factor (p < 0.05)." (PMID 37575983, 2023). "CRP, which is generated by liver cells in response to an increase in IL-6 production by macrophages and adipocytes, is a sensitive marker for systemic inflammation and is implicated in the etiology of numerous chronic disorders, such as obesity and coronary heart disease." (PMID 37734921, 2023). "Moreover, obesity was shown to be associated with a low-grade inflammation that stimulates inflammatory cytokine release, including tumor necrosis factor, interleukin-6, and C-reactive protein (CRP)." (PMID 36498548, 2022). "Furthermore, high levels of CRP are associated with obesity and insulin resistance." (PMID 35361818, 2022). "Moreover, the study did not account for potential confounders of the CRP-walking limitations association (e.g., comorbidities) which may have biased the estimates of associations between obesity, CRP and walking limitations." (PMID 35301057, 2022). "C3 and CRP may be useful clinical biomarkers of risk or treatment targets in women with obesity." (PMID 35306495, 2022).
Obesity (continued). "It has been suggested that obesity is associated with an impairment of adipocyte metabolism, accompanied by recruitment of macrophages into the adipose tissue, causing local and systemic inflammation, and inducing production of acute-phase proteins, such as CRP." (PMID 35205011, 2022). "There are no international reference values for phase angle; however, a 5.4–5.7° range has been suggested for healthy adults and altered measurements could be associated with inflammatory markers in people with obesity and type 2 diabetes like C reactive protein." (PMID 34943423, 2021). "Furthermore, an increase in the levels of inflammatory markers, such as C-reactive protein (CRP) and fibrinogen, and white blood cell count associated with abdominal obesity may contribute to insulin resistance in individuals with obesity." (PMID 34641407, 2021). "Thus, the inverse association between plasma adiponectin and hs-CRP levels may indicate that reduced adiponectin production contributes to systemic and vascular inflammation in obesity." (PMID 33946540, 2021). "In addition, obesity, especially visceral obesity, is associated with increased CRP." (PMID 34527685, 2021). "We further found that obesity was associated with lower FEV1, FVC and higher FEV1/FVC ratio only in the highest insulin resistance/CRP tertile, indicating that both insulin resistance and low-grade chronic inflammation may lie on the association pathway between obesity and pulmonary function." (PMID 34272443, 2021). "Obesity is considered as a condition of chronic subacute systemic inflammation which is associated with an increased synthesis of pro-inflammatory cytokines by both adipocytes and macrophages of the adipose tissue (interleukin (IL)-1β, tumor necrosis factor-α (TFNα), CRP)." (PMID 34621378, 2021). "Thus, TNFα, IL-6, and CRP are well known markers of obesity-associated inflammation and disease." (PMID 33986456, 2021). "In addition, according to our results, in a study carried out in 26,016 middle-aged and older adults (>35 years old) with metabolic syndrome in Taiwan, obesity, high body fat, high WC or hip circumference, and high WHtR were significantly associated with increased odds ratios of high CRP and NLR." (PMID 32210070, 2020). "We further conducted stratification analyses by obesity, sex-hormone and breast cancer subtype to determine whether these lifestyle and pathologic factors modified the association between genetically elevated CRP and breast cancer risk." (PMID 33614510, 2020). "The association between CRP and atherosclerosis might be diminished in subjects with obesity." (PMID 32646381, 2020). "This is because obesity is associated with a chronic inflammatory response, which is characterized by abnormal cytokine production, increased synthesis of acute-phase reactants, such as C-reactive protein (CRP), and the activation of proinflammatory signaling pathways." (PMID 32824322, 2020). "Obesity is associated with a low-grade chronic inflammatory state, characterized by the activation of proinflammatory signalling pathways, increased synthesis of acute-phase reactants, such as C-reactive protein (CRP), and increased proinflammatory cytokines production." (PMID 31779136, 2019). "Furthermore, prior studies have indicated that increased oxidative stress and elevated inflammatory markers such as C-reactive protein (CRP) in women with PCOS are correlated with obesity, insulin resistance, and an increased risk of cardiovascular disease (CVD)." (PMID 31139144, 2019). "In addition, obesity is associated with relatively higher levels of prothrombotic and inflammatory markers (e.g., plasminogen activator inhibitor-1 antigen, fibrinogen, and C-reactive protein), which are associated with IS." (PMID 31118920, 2019). "While obesity and loneliness have been studied as separate risk factors for CRP, it is uncertain whether they operate as independent risk factors for clinically elevated CRP." (PMID 30439985, 2018).
Obesity (continued). "Univariate linear regression analysis indicated that race, liver function, obesity, hypertension, dyslipidemia, smoking, physical activity, vigorous recreational activity, 2-hour glucose, HbA1C, high-density lipoprotein, triglyceride, vitamin D, and CRP were significantly associated with HOMA-IR." (PMID 30013028, 2018). "Race, liver function, obesity, hypertension, dyslipidemia, smoking, physical activity, vigorous recreational activity, 2-hour glucose, hemoglobin A1C (HbA1C), high-density lipoprotein, triglyceride, vitamin D and C-reactive protein were covariates significantly associated with HOMA-IR." (PMID 30013028, 2018). "Interestingly a CRP value greater than 3 mg/L at disease diagnosis was associated with the presence of carotid plaques after adjusting for age, sex, obesity, hypertension, dyslipidemia, and smoking (odds ratio 5.56, 95% confidence interval 1.11–28.77; p = 0.03)." (PMID 29666651, 2018). "In addition, inflammatory mediators such as C-reactive protein and interleukin-6 may contribute to the obesity-related bladder cancer risk as suggested by positive relation of circulating levels of inflammatory markers to bladder cancer mortality." (PMID 28389625, 2017). "It is assumed that the major components of MS - obesity, insulin resistance, dyslipidemia, and hypertension - are linked to renal damage through the systemic release of several pro-inflammatory mediators, such as uric acid (UA), C-reactive protein (CRP), and generalized oxidative stress." (PMID 29321950, 2017). "The study was also limited by the lack of information on other biological makers, such as serum triglycerides, C-reactive protein, glucose, insulin, and cholesterol, which could have provided an input to the interpretation of the associations between FAs and obesity." (PMID 28465289, 2017). "However, regression analysis did not support that these two inflammatory markers were independently associated with the HOMA-IR and DIOGTT, indicating that elevated TNFα and CRP may play a role by mediating other risk factors for T2D such as obesity." (PMID 28713332, 2017). "More broadly, it is unclear whether these relatively slight differences in CRP would be measurable in populations with higher rates of inflammation associated with obesity, or if these patterns would hold in populations living in environments with easy access to quick calories." (PMID 28003312, 2017). "In addition to excess body weight, the present study confirmed that many of the conventional CVD risk factors including elevated LDL-cholesterol, increasing age, smoking, low level of physical activity and overweight/obesity were associated with an increased risk for elevated CRP." (PMID 27827910, 2016). "Obesity has been discovered to be associated with excess adipocyte hypertrophy generating a proinflammatory state through secretion of inflammatory cytokines and chemokines, including interleukin (IL)-1β, IL-6, IL-8, monocyte chemoattractant factor, tumor necrosis factor-α, and C-reactive protein." (PMID 26658675, 2015). "Whereas obesity favors the production of M1 macrophages, which is associated with reduced adiponectin mRNA expression by the infiltrated adipose tissue and elevations in circulating IL-6 and CRP, adiponectin promotes a shift to the M2 phenotype and so is an anti-inflammatory adipokine." (PMID 26516917, 2015). "One hallmark of obesity is a systemic low-grade inflammation with increased levels of many inflammatory markers such as C-reactive protein (CRP), interleukin- (IL-) 6, tumor necrosis factor- (TNF-) α, and leptin, and this is maybe important for the pathogenesis of obesity-related asthma." (PMID 26538828, 2015). "CRP-mfs might be used as an obesity-associated inflammatory marker." (PMID 25299074, 2014).
Obesity (continued). "Indeed, both hypoadiponectinemia and hyperleptinemia, two adipokine disturbances common in subjects with obesity and insulin resistance, have been linked to increased hepatic production of CRP, as well as augmented in situ synthesis of CRP in vascular endothelial cells in hyperleptinemia." (PMID 27433484, 2014). "The 2‐year follow‐up of the Identification and prevention of Dietary‐ and lifestyle‐induced health Effects in Children and InfantS (IDEFICS) cohort allowed to test whether higher baseline levels of hs‐CRP were associated with higher body mass and increased incidence of overweight/obesity over time." (PMID 23744403, 2013). "Hence the explanation for the association between both obesity and CRP with a range of chronic disease outcomes could be because of the effect of obesity on an individual’s inflammatory responsiveness." (PMID 23391158, 2013). "Furthermore, an association has been reported of several SNPs in the CRP gene with T2D, suggesting that this may be a candidate gene involved in the development of T2D, a frequent disease in individuals with obesity." (PMID 23049543, 2012). "C-reactive protein was one of the mediators of the association between gingivitis and obesity suggesting that the presence of a low-grade systemic inflammation due to obesity may trigger increased local inflammatory response to external stimuli such as dental plaque." (PMID 22671969, 2012). "Elevated CRP—defined as a risk factor for CVD42—seems to be linked to obesity, as excess adipose tissue releases inflammatory cytokines that may lead to higher CRP levels and to higher levels of the prothromotic factors plasminogen activator inhibitor (PAI)-1 and fibrinogen." (PMID 22804097, 2012). "Highly sensitive CRP, a marker of inflammation, was associated with survival, increased with tumour stage and may have reflected inflammation in the tumour as well as that due to obesity." (PMID 21081932, 2011). "Indeed, obesity is associated with high CRP and fibrinogen and lower lung function and may provide another link between systemic inflammation and low lung function." (PMID 20625390, 2010). "To determine whether sarcopenia/obesity associations with inflammation in the two age groups are in concordance with their associations with insulin resistance and dysglycemia, we examined log CRP as outcome in parallel linear regression models." (PMID 22421977, 2010). "Also in line with the literature describing differential impacts of SES on obesity in middle-income countries, we found that adjusting for adiposity fully attenuated the association between maternal education and CRP levels in women but strengthened the same association in men." (PMID 20137842, 2010). "Relevant research on CRP isoforms, mCRP development, cellular targets, and their involvement in obesity-related inflammation was included and examined." (PMID 42255886, 2026). "This review examines the role of monomeric CRP (mCRP) as a mediator of ongoing inflammation in obesity and discusses the mechanisms through which it contributes to endothelial dysfunction, immune activation, and metabolic changes." (PMID 42255886, 2026). "The other study that enrolled a sample from the same demographic subset of postmenopausal women with overweight or obesity only measured CRP and showed a statistically significant reduction in this marker in the intervention group compared to placebo." (PMID 41515260, 2026). "Our research provides support for high-intensity interval training as an efficient approach to lowering CRP in children with obesity." (PMID 41590696, 2026). "In acute COVID-19, patients with obesity exhibit higher initial and peak CRP, ESR, and d-dimer, suggesting a more exuberant inflammatory response." (PMID 41543809, 2026). "Elevated CRP levels contribute to heightened insulin resistance and increased lipogenesis, thereby creating a vicious cycle that worsens obesity." (PMID 41590696, 2026).
Obesity (continued). "In the cross‐sectional analysis, higher irisin levels were associated with higher odds of obesity, abdominal obesity and sarcopenic obesity; however, these associations lost significance after further adjustment for HOMA‐IR, CRP and adiponectin." (PMID 41457869, 2026). "Accordingly, obesity is characterised by high levels of circulating inflammatory mediators, such as CRP, which is inversely correlated with serum iron levels in humans." (PMID 41275403, 2026). "In fact, obesity can impact serum concentrations of pro-inflammatory mediators [such as IL-6, CRP, TNF-α, resistin, and leptin] and anti-inflammatory mediators (Adiponectin and IL-10) in individuals with periodontitis." (PMID 40422620, 2025). "Subgroup analyses showed more pronounced CRP reductions in individuals with higher baseline CRP levels (>4.5 mg/L), obesity, younger age, and those participating in longer-term interventions." (PMID 40871683, 2025). "While obesity was achieved in all studies, the accompanying effects varied: some animals displayed dyslipidemia, elevated serum CRP concentration or other inflammatory markers, or varying degrees of hepatic inflammation." (PMID 40770069, 2025). "This is in line with a previous study that reported lowest CRP levels for overweight children that transitioned to normal weight, and highest CRP concentrations for children with manifest obesity." (PMID 39899498, 2025). "Despite these limitations, this study offers important evidence supporting the utility of salivary CRP as a predictive biomarker for obesity‐related inflammation." (PMID 40547317, 2025). "For example, the HRs (95% CIs) for overweight and obesity compared to normal BMI were 1.13 (1.05‐1.23) and 1.30 (1.19‐1.42), respectively, before adjusting for ln (CRP), and 1.13 (1.04‐1.22) and 1.28 (1.16‐1.40) after adjustment." (PMID 39791283, 2025). "Sex wasfound to moderate the relationships between obesity, depressive symptoms, and NLRand CRP levels." (PMID 40926826, 2025). "Individuals with obesity were also classified as having high inflammation if their circulating levels of IL-6 and CRP were higher than the average in the lean, healthy controls (5.4 pg/mL for IL-6 and 0.67 mg/dL for CRP)." (PMID 40548377, 2025). "Broad risk factors include age, lifestyle habits, metabolic syndrome, obesity, hypersensitivity C-reactive protein, high fibrinogen levels, and alterations in these markers, which can influence clinical outcomes in PIS patients, though they lack specificity." (PMID 41013845, 2025). "Themeasures of obesity and high-sensitivity C-reactive protein (hs-CRP) levels wereelevated in the OSA group, both for EDS and non-EDS patient groups." (PMID 40776960, 2025). "Our results suggest that simvastatin does not exert additional antidepressive effects when added to escitalopram in patients with comorbid MDD and obesity, despite significantly lowering lipids and CRP level." (PMID 40465256, 2025). "A meta-analysis found that moderate-intensity aerobic exercise performed for at least 150 min per week lowers hs-CRP levels by up to 30% in individuals with obesity." (PMID 40699756, 2025). "Gal‐3 is positively correlated with obesity and inflammation, as measured by inflammatory markers IL‐6 and CRP." (PMID 41404534, 2025). "Hs-CRP showed a modest separation in CI ranges (0.09–0.33 in obesity vs. 0.06–0.15 in controls/overweight) with a p-value approaching significance (p = 0.076), suggesting a possible trend toward higher systemic inflammation in obesity." (PMID 40868054, 2025). "Meta-inflammation was shown in the HFFC group by elevated serum concentrations of the acute phase protein C-reactive protein for more than 60 days during development of obesity, accompanied by increased numbers of circulating neutrophils and monocytes." (PMID 40770069, 2025).